ABCG2 (ATP binding cassette subfamily G member 2 (JR blood group))
Diseases named in the same sentence as ABCG2 in open-access papers (continued):
Sharing a sentence is not in itself a finding about the gene and the disease.
glioblastoma (continued). "Our data demonstrated that either suppressing miR-381 or enforcing NEFL expression inhibited the expression of multidrug resistance factors (ABCG2, ABCC3, and ABCC5) in glioblastoma cells in the presence of TMZ." (PMID 25605243, 2015). "Both CD133- and ABCG2-positive cells were sparsely distributed throughout the glioblastoma tissues and both CD133 and ABCG2 were localized to both the cytoplasm and cytomembrane." (PMID 26563263, 2015). "We next performed immunohistochemical analysis to investigate the expression levels of stemness (CD133, ABCG2) and differentiation-related markers (GFAP) in human glioblastoma tissues." (PMID 26563263, 2015). "In glioblastoma multiforme (GBM) stem cells, the high expression of ABCG2 leads to decreased accumulation of Ce6, which may limit the effectiveness of PDT." (PMID 39337463, 2024). "Ibudilast sensitised glioblastoma cells to temozolomide by inhibiting the macrophage migration inhibitory factor, while sildenafil is included on the basis of its ability to inhibit drug transporters ABCB1 and ABCG2." (PMID 34575827, 2021). "To study a correlation between promoter methylation and gene expression, we analyzed MGMT, ABCB1 and ABCG2 expression in 20 glioblastoma and 7 non-neoplastic brain samples." (PMID 24380367, 2013). "miRNA-381 may target multidrug resistance proteins (ABCG2, ABCC3, ABCC5) and stemness factors, enhancing glioblastoma sensitivity to temozolomide, while reducing the molecular level of miRNA-318 can lead to drug resistance in glioblastoma." (PMID 40675967, 2025). "Additionally, a previous study revealed that inhibiting Abcg2, another gene in the ABC transporter family, increased PPIX fluorescence in U87MG cells (a specific glioblastoma cell line derived from human malignant glioblastoma multiforme, a type of brain tumor)." (PMID 39409147, 2024). "However, some TMZ-resistant glioblastoma cells exhibit increased levels of ABCB1 and ABCG2." (PMID 29186899, 2017). "ABCB1 and ABCG2 promoter methylation have not been assessed in glioblastoma patients before." (PMID 24380367, 2013). "However, in contrast to MGMT methylation no data have existed for ABCB1 and ABCG2 promoter methylation in glioblastoma tissue until now." (PMID 24380367, 2013). "By improving the physicochemical properties of GDC-0941, such that it bypassed ABCB1 and ABCG2 efflux, GNE-317 (an improved version of GDC-0941) effectively decreased tumor growth in all glioblastoma models tested, regardless of the BBB integrity and function." (PMID 29186899, 2017). "In glioblastoma patients, currently available EGFR inhibitors do not provide a survival benefit but could be used to overcome blood-brain barrier ABCB1/ABCG2-mediated drug resistance via transporter internalization/degradation." (PMID 36973040, 2023).
melanoma (62 papers, 2008 to 2026). A malignant, usually aggressive tumor composed of atypical, neoplastic melanocytes. "Prior studies have reported ABCG2, an ABC transporter implicated in multidrug resistance, as having potential to increase BRAFi resistance in melanoma." (PMID 38213996, 2024). "Several cell-surface markers have been linked to melanoma CSCs’ self-renewal capacity, including ABCG2, ABCB5, ALDH, CD133, CD20, CD166, CD271 and Nestin." (PMID 38201651, 2024). "RT-PCR analysis of Melanoma Associated Antigens (MAA) expressed by melanoma cell line IGR39 sorted for its expression of ABCG2 and then treated with 5-AZA-CdR." (PMID 21203549, 2010). "Interestingly, several of these AhR‐associated genes have been involved in the aggressiveness of melanoma or other cancers and have been associated with a poor prognosis (ABCG2, COL1A1, COL6A1, COL6A2, TGFBI)." (PMID 36305167, 2022). "MSLC-activated neutrophils impart unique stem cell characteristics to melanoma cells, enhancing ABCG2 (ATP-binding cassette sub-family G member 2) expression and capacity to form melanospheres." (PMID 40399946, 2025). "In our laboratory, we demonstrated that the natural compound δ-tocotrienol decreases the ability of melanoma cells to form melanospheres and promotes the disaggregation of melanospheres, suppressing the expression of the ABCG2 marker." (PMID 39199632, 2024). "ABCG2 was found to be highly expressed, together with other stemness markers, in melanoma tissues and to correlate with the clinical features of patients and a worse prognosis." (PMID 39199632, 2024). "To obtain further insights into the mechanism by which TGFβ regulates markers implicated in melanoma stemness, we examined the TGFβ-mediated regulation of specific melanoma CSC markers (ALDHA1, ALDHA3, CD133 and ABCG2) at the transcriptional level." (PMID 38201651, 2024). "To confirm that RIPK4, through the regulation of ABCG2 expression, is crucial for the sensitivity of melanoma cells to CisPt and DOX treatment, we conducted RIPK4 overexpression in A375 cells." (PMID 39766280, 2024). "The expression of ABCG2 has been observed in various tumours, including melanoma, suggesting that ABCG2 represents a common mechanism of clinical drug resistance." (PMID 39766280, 2024). "ABCG2 is another ABC drug efflux transporter associated with drug resistance and stemness in different types of tumors, such as melanoma." (PMID 39199632, 2024). "Our previous studies have shown that downregulation of RIPK4 impairs signalling pathways important for the survival and progression of melanoma, such as NFκB and Wnt/β-catenin, which are also involved in the regulation of ABCG2 protein levels." (PMID 39766280, 2024). "Our group has shown that GH elevates the specific ABC transporters, such as ABCC1, ABCC2, ABCB1, and ABCG2 in melanoma, hepatocellular carcinoma, and pancreatic cancer." (PMID 39123364, 2024). "This analysis showed variable RNA expression of the three efflux transporter genes ABCB1 (P-gp), ABCB4 (MDR3) and ABCG2 (BCRP) across the melanoma cell line panel." (PMID 38226983, 2024). "Our data demonstrate that inhibition of ABCG2 with either GF-120918 (elacridar) or KO-143 increases melanoma cell sensitivity to PLX-4032." (PMID 35944584, 2022). "We then conducted a MDR efflux assay and found that SOX2 silencing strongly counteracted the efflux activity of BCRP/ABCG2 transporter induced by PLX4032 in all BRAFV600E melanoma cells tested." (PMID 35944584, 2022). "For examples, in melanoma, Notch4 interacts with CSCs expressing CD133 and ABCG2 and this promotes CSCs to form melanoma." (PMID 35903544, 2022). "It was previously shown that GH action in GHR+ human melanoma cells upregulates while GHR knockdown suppresses the ABC-transporter system, especially ABCB1, ABCB5, ABCB8, ABCC1, ABCC2, ABCG1, and ABCG2 differentially in a drug-dependent manner." (PMID 31547367, 2019).
melanoma (continued). "Among the regulated genes, we choose ABCG2, because the transcript of this gene was found very abundant in melanoma metastasis samples from patients." (PMID 23559012, 2013). "The strict relationship between MCSCs and metastasis was further reinforced by the finding that deparaffinized melanoma metastasis samples contained ABCG2 levels significantly higher than primary melanoma samples." (PMID 23559012, 2013). "In fact, we find that a large percentage of ABCG2-positive melanoma cells with known CSC properties, also express CXCR6." (PMID 21203549, 2010). "In particular, in regards to melanoma, ABCB5 is overexpressed in melanoma and ABCG2 is expressed by a sub-fraction of CD133-positive melanoma cell population." (PMID 21203549, 2010). "In a recent paper, our group published that ABCG2 is expressed by a subpopulation of human melanoma cells (cell line WM115) expressing high level of CD133." (PMID 21203549, 2010). "We extended this analysis of ABCG2 to two additional melanoma cell lines derived from the same melanoma patient: primary melanoma cell line IGR39 and the related metastatic line IGR37." (PMID 21203549, 2010). "In particular, ABCB5 is overexpressed in melanoma, and ABCG2 is expressed by a subcellular CD133-positive melanoma cells." (PMID 21203549, 2010). "In this regard, it is important to emphasize that our analysis of human melanoma biopsies confirmed the presence of a ABCG2+/CXCR6+ subfraction in human tissues." (PMID 21203549, 2010). "RT-PCR analysis of Melanoma Associated Antigens (MAA) expressed by melanoma cell lines IGR37 and IGR39 sorted for its expression of CXCR6 and double positive ABCG2/CXCR6 IGR37 cells and in tumor xenograft engrafted with CXCR6+ IGR37 cells." (PMID 21203549, 2010). "Consistent with previous observations with WM115 human melanoma cells and melanoma biopsies, ABCG2 expression was undetectable in all the tumor xenograft cell preparations (data not shown)." (PMID 21203549, 2010). "CXCR6 identifies a more discrete subpopulation of cultured human melanoma cells with a more aggressive MCSC phenotype than cells selected on the basis of the ABCG2+ phenotype alone." (PMID 21203549, 2010). "We looked for co-association of CXCR6 expression and ABCG2 expression with MCSC activity and evidence for the descent of melanoma CSCs from TSSCs." (PMID 21203549, 2010). "RT-PCR analysis of Melanoma Associated Antigens (MAA) expressed by the melanoma cell cultures IGR37 and IGR39 unsorted and sorted for ABCG2 expression." (PMID 21203549, 2010). "Resistance in melanoma BMs with BRAFV600 mutations is primarily mediated by drug efflux transporters, including P-glycoprotein (P-gp; ABCB1) and breast cancer resistance protein (BCRP; ABCG2), located at the BBB and impeding penetration into BMs." (PMID 40076927, 2025). "Similarly, high levels of ABCG2, known as breast cancer resistance protein (BCRP), have been associated with MDR in NSCLC, melanoma, breast, colorectal, ovarian, and gastric cancers." (PMID 38893104, 2024). "Moreover, it has been shown that melanoma cells resistant to vemurafenib express high levels of ABCG2 and CD271." (PMID 39199632, 2024). "Additionally, we showed that the protein levels of ABCC1, ABCC2, ABCB1, and ABCG2 were elevated in presence of GH treatment in parent melanoma cells (Malme-3M and SK-MEL-28)." (PMID 39123364, 2024). "Breast cancer resistance protein 1 (BCRP/ABCG2) is a drug efflux ABC-transporter with complementary action to P-gp, which is associated with resistance to many cancer therapies and also reportedly expressed in melanoma tissue and cell lines." (PMID 38226983, 2024). "Moreover, CD133+ and ABCG2+ melanoma stem cells were shown to overexpress proangiogenic factors and to be characterized by tube-formation capacity." (PMID 39199632, 2024).
melanoma (continued). "Accordingly, IFN-active melanoma cells overexpress the multi-drug resistance pump ABCG2 and interferon-related genes (e.g., PD-L1 and HLA-A, -B, and -C), irrespective of the presence of cytokines in vitro, conferring a potential cross-resistance to in vivo MAPKi and immunotherapy." (PMID 36497341, 2022). "Remarkably, we revealed that N2-polarized neutrophils could confer stem-like traits to melanoma cells, by promoting their spheroidogenic ability as well as the expression of ABCG2." (PMID 35884452, 2022). "We found that pharmacological inhibition of the drug efflux transporter BCRP/ABCG2 with either 1 μM GF-120918 (elacridar) or 5 μM KO-143 led to increased melanoma cell sensitivity to PLX4032 in SOX2-expressing A375 and A2058 cells, without impacting on that of SOX2-depleted cells." (PMID 35944584, 2022). "We hypothesize that MDR induced by BRAFi in melanoma cells could be promoted by SOX2 through a direct transcriptional regulation of ABCG2." (PMID 35944584, 2022). "Other potential markers that could be used for the identification of melanoma CSCs are members of ABC family (ABCG2, ABCB5), CD166, and nestin." (PMID 33424978, 2020). "Moreover, it was reported that in melanoma stem cells, concomitant occurrence of ABCG2 and CD133 can be a stemness marker." (PMID 28623509, 2017). "In the same way, ABCG2 mRNA was upregulated in melanoma cells that over expressed FKBP51 (upper)." (PMID 23559012, 2013). "Indeed, melanoma spheroid cells displayed the same expression pattern as their adherent counterparts with the exception of ABCG2, which was expressed by 63.6% of SLM8 adherent cells." (PMID 21526207, 2011). "Interestingly, ABCG2+ melanoma cells, that possess the capacity to self-renew and generate the heterogeneous cancer cells, contain intracytoplasmic FKBP51 at higher levels than ABCG2- cells." (PMID 22087835, 2011). "Therefore, we investigated 4 uncultured human melanoma positive lymph node biopsy specimens for the presence of cells with the CXCR6+/ABCG2+ phenotype." (PMID 21203549, 2010). "Moreover, like ABCG2-expressing melanoma cells, CXCR6-expressing cells are a small fraction of cells in cultures of primary, metastatic melanoma cell lines and human melanoma biopsy specimens." (PMID 21203549, 2010). "Therefore, herein, we have addressed the following question: Can TAAs, currently utilized as targets in melanoma immunotherapeutic protocols, be used to target ABCG2-positive or CXCR6-positive cells?" (PMID 21203549, 2010). "In addition, the treatment with the DNA hypomethylating agent 5-aza-2’-deoxycytidine was able to induce a de novo expression of MAGE-A3, MAGE-A4, GAGE 1-2, GAGE 1-6 and SSX 1-5 in both ABCG2+ and ABCG2- IGR37 melanoma cells." (PMID 21203549, 2010). "Notably, we could also observe that CSC-activated neutrophils could endow melanoma cells with peculiar stemness traits (i.e., ABCG2 expression and melanosphere formation)." (PMID 39199632, 2024). "Thus, the relationship between melanoma formation and ABCG2 and CXCR6 expression was investigated." (PMID 21203549, 2010). "In addition, the treatment with the DNA hypomethylating agent 5-aza- 2’-deoxycytidine was able to induce a de novo expression of MAGE-A3, MAGE-A4, GAGE 1-2, GAGE 1-6 and SSX 1-5 in both ABCG2+ and ABCG2- melanoma cells derived from the same parental cell culture." (PMID 21203549, 2010). "Finally, we have characterized the subpopulation ABCG2+/ABCG2- and CXCR6+/CXCR6- of melanoma for the expression of melanoma associated antigens (MAA) in view of a possible immunotherapeutic approach against more aggressive subpopulations expressing ABCG2 and/or CXCR6." (PMID 21203549, 2010). "Gene expression analysis based upon CCLE data, showed a number of the melanoma cell lines express ABCB1, ABCB4 and ABCG2 transcripts, however levels varied widely." (PMID 38226983, 2024).
melanoma (continued). "ABCG2+ and CD133+ melanoma cells were reported to secrete proangiogenic factors such as VEGF and its receptor VEGFR-2, Tie2, angiopoietin and MMP-2/-9." (PMID 39199632, 2024). "E2F1 promotes chemoresistance by inducing the expression of ABC transporter ABCG2 and confers anticancer drug resistance by activating ABC transporter family members (ABCA2 and ABCA5) and Bcl-2 in malignant melanoma cells." (PMID 36833320, 2023). "In this study, we also provide evidence that SOX2 desensitizes melanoma cells to BRAF inhibition, likely by decreasing intracellular drug accumulation through transcriptional activation of the ABCG2/BCRP drug efflux transporter." (PMID 35944584, 2022). "In human SK-MEL-30 melanoma cells treated with 250 ng/mL hGH in vitro increased expression of ABCB5, ABCB8, ABCG1 and ABCG2 RNA." (PMID 33291663, 2020). "We observed that doxorubicin, cisplatin, paclitaxel, oridonin, and vemurafenib, in four different human melanoma cell lines, in presence of GH differentially upregulated ABCB1, ABCB5, ABCB8, ABCC1, ABCC2, ABCG1, and ABCG2 multi-drug efflux pump expressions." (PMID 32382711, 2019). "In human melanoma cells, coexistence of ABCB1, ABCG2, and ABCC2 together with stem cell markers on the cell surface was observed in a subset of cells." (PMID 28623509, 2017). "In melanoma, different markers have been employed to characterize the putative melanoma CSC and, particularly, CD133, CD271, CD146, ALDH, ABCB5, ABCG2, Nestin and CD117 were considered." (PMID 28125999, 2017). "Out of four, two ABC transporter protein expressions, ABCG2 and ABCB5, have been identified in potential melanoma stem cells." (PMID 27054115, 2016). "PLX4032 and PLX4720 also sensitised two wild-type BRAF melanoma cell lines, IPC-298 and SK-Mel-30 (DSMZ, Braunschweig, Germany), that express ABCB1, ABCC1, and ABCG2 to vincristine and mitoxantrone." (PMID 25300205, 2014). "This is of relevance for the design of next-line therapies for melanomas with acquired PLX4032 resistance since ABC transporters including ABCB1, ABCC1, and ABCG2 confer multi-drug resistance." (PMID 25300205, 2014). "The ectopic overexpression of Oct-3/4 in melanoma cell lines was also effective to enhance their expression of stem cell-like markers such as CD271, MDR1, ABCG2, ABCB5, Kruppel-like factor 4 (KLF4) and Nanog and self-renewal capacity." (PMID 23301832, 2013). "In recent publications, one of us identified aggressive subpopulations expressing two stem cell markers, ABCG2 and CXCR6, in human melanoma cell lines, making this tumor a suitable candidate to test our theory." (PMID 22275856, 2012). "In this report, we investigated a new candidate for a melanoma cancer stem cell (MCSC) marker, the cytokine co-receptor CXCR6, with respect to the properties of ABCG2-expressing MCSCs." (PMID 21203549, 2010). "Monzani and colleagues further showed that cancer stem-like cells derived from the melanoma cell line highly co-expressed CD133 and ABCG2 markers with enhanced tumorigenic potential." (PMID 18612434, 2008). "Vemurafenib is one of the substrates of ABCG2, and it was suggested that this transporter could influence BRAF resistance acquisition in melanoma cells." (PMID 39175042, 2024). "A similar, but not significant, increase in ABCB1 and ABCG2 was observed in the melanoma recipient cells when administered with ExoGH, Exodoxo, and ExoGH+doxo as compared with the controls." (PMID 39123364, 2024). "As FKBP51 has shown to positively regulate EMT, and ABCG2+ melanoma cells contained high FKBP51 levels, we hypothesized that ABCG2+ cells expressed EMT genes." (PMID 23559012, 2013). "In vivo CXCR6+ melanoma cells produced a tumor in less time than ABCG2+ cells and, more interestingly, the negative subpopulation did not give a tumor." (PMID 21203549, 2010). "Although the evaluated melanoma cell lines were derived from human tumor tissues, the newly described CXCR6+/ABCG2+ cell phenotype might have been limited to cultured tumor cells." (PMID 21203549, 2010).